ENSG00000266953 (novel protein, readthrough between GPI and PDCD2)
Gene: Protein-coding gene on chromosome 19 (34,396,315 to 34,409,364, forward strand). Ensembl gene ENSG00000266953.
Genetic constraint (gnomAD): Loss-of-function variants: 17 observed, 17.4 expected, observed/expected ratio (o/e) 0.98, 90% interval 0.67 to 1.46. Missense variants: 271 observed, 284.82 expected, observed/expected ratio (o/e) 0.95, 90% interval 0.86 to 1.05. Synonymous variants: 114 observed, 110.73 expected, observed/expected ratio (o/e) 1.03, 90% interval 0.88 to 1.2.